CNOT12 (CCR4-NOT transcription complex subunit 12)
Synonyms: TNKS1BP1; KIAA1741; TAB182; FLJ45975
Tractability: Antibody: the Human Protein Atlas places it where antibodies can reach. PROTAC: ubiquitination databases record sites on it; its protein half-life has been measured.
Gene: Protein-coding gene on chromosome 11 (57,299,630 to 57,325,682, reverse strand). Ensembl gene ENSG00000149115.
Subcellular location: Nucleus; Cytoplasm, cytoskeleton; Chromosome
Subcellular location (Human Protein Atlas): Plasma membrane
Pathways (Reactome):
Developmental Biology: M-decay: degradation of maternal mRNAs by maternally stored factors
Metabolism of RNA: Deadenylation of mRNA
Gene Ontology:
Molecular function: ankyrin repeat binding; cadherin binding; enzyme binding; protein binding; protein serine/threonine kinase activator activity; protein-containing complex binding
Biological process: cellular response to ionizing radiation; double-strand break repair; nuclear-transcribed mRNA poly(A) tail shortening; telomere maintenance via telomerase
Cellular component: adherens junction; CCR4-NOT complex; cytoplasm; heterochromatin; nucleus; cytosol; chromosome; cytoskeleton
Genetic constraint (gnomAD): Loss-of-function variants: 48 observed, 139.35 expected, observed/expected ratio (o/e) 0.34, 90% interval 0.27 to 0.44. The upper end of that interval is the gene's LOEUF score, 0.44, which puts it in group 1 of 6, group 1 being the genes least tolerant of losing a copy. Missense variants: 2,149 observed, 2,256.5 expected, observed/expected ratio (o/e) 0.95, 90% interval 0.92 to 0.99. Synonymous variants: 875 observed, 907.48 expected, observed/expected ratio (o/e) 0.96, 90% interval 0.91 to 1.02.
Homologues: Orthologues: chimpanzee TNKS1BP1 (99% identical), macaque TNKS1BP1 (96% identical), dog TNKS1BP1 (76% identical), rabbit TNKS1BP1 (73% identical), mouse Tnks1bp1 (71% identical), rat Tnks1bp1 (70% identical), guinea pig TNKS1BP1 (57% identical), zebrafish si:dkey-9i23.6 (7% identical). Paralogues in human: KIAA1671 (16% identical).
Diseases named in the same sentence as CNOT12 in open-access papers:
CNOT12 is named in the same sentence as 23 diseases in open-access papers, as found by Europe PMC text mining. Sharing a sentence is not in itself a finding about the gene and the disease.
CNOT12 shares sentences with these, for which no sentence is quoted: cancer (10 papers); tumor (8); esophageal squamous cell carcinoma (4); breast carcinoma (3); lung adenocarcinoma (3); pancreatic cancer (3); triple-negative breast carcinoma (3); adenovirus infection (2); colorectal cancer (2); gastric cancer (2); infection (2); lung carcinoma (2); arrhythmogenic right ventricular cardiomyopathy (1); basal cell carcinoma (1); esophageal tumor (1); gastritis (1); hepatocellular carcinoma (1); leukemia (1); liver cancer (1); lymph node metastasis (1); ovarian carcinoma (1); prostate carcinoma (1); viral infection (1).